GPD2 (glycerol-3-phosphate dehydrogenase 2)
Description:
Calcium-responsive mitochondrial glycerol-3-phosphate dehydrogenase which seems to be a key component of the pancreatic beta-cell glucose-sensing device.
Synonyms: mGDH; GDH2; GPDM; mGPDH
Tractability: Small molecule: an approved drug acts on it; it belongs to a druggable protein family. PROTAC: ubiquitination databases record sites on it; its protein half-life has been measured.
Target class: Enzyme; Oxidoreductase
Gene: Protein-coding gene on chromosome 2 (156,435,290 to 156,613,735, forward strand). Ensembl gene ENSG00000115159.
Subcellular location: Mitochondrion
Subcellular location (Human Protein Atlas): Mitochondria
Pathways (Reactome):
Metabolism: Synthesis of PA; Triglyceride catabolism
Gene Ontology:
Molecular function: glycerol-3-phosphate dehydrogenase (quinone) activity; calcium ion binding
Biological process: glycerol-3-phosphate metabolic process; glycerol-3-phosphate shuttle; glycerol catabolic process
Cellular component: mitochondrion; mitochondrial inner membrane
Genetic constraint (gnomAD): Loss-of-function variants: 24 observed, 42.42 expected, observed/expected ratio (o/e) 0.57, 90% interval 0.41 to 0.8. The upper end of that interval is the gene's LOEUF score, 0.8, which puts it in group 3 of 6, group 1 being the genes least tolerant of losing a copy. Missense variants: 460 observed, 592.77 expected, observed/expected ratio (o/e) 0.78, 90% interval 0.72 to 0.84. Synonymous variants: 197 observed, 206.07 expected, observed/expected ratio (o/e) 0.96, 90% interval 0.85 to 1.08.
Homologues: Orthologues: chimpanzee GPD2 (100% identical), macaque GPD2 (99% identical), dog GPD2 (96% identical), guinea pig GPD2 (96% identical), rabbit GPD2 (94% identical), pig GPD2 (94% identical), mouse Gpd2 (93% identical), rat Gpd2 (92% identical), tropical clawed frog gpd2 (83% identical), zebrafish gpd2 (80% identical), Drosophila melanogaster Gpo1 (61% identical), Caenorhabditis elegans gpdh-3 (58% identical), and 3 more.
Diseases named in the same sentence as GPD2 in open-access papers:
GPD2 is named in the same sentence as 63 diseases in open-access papers, as found by Europe PMC text mining. Sharing a sentence is not in itself a finding about the gene and the disease. The quoted sentences say what the papers report.
thyroid cancer (9 papers, 2019 to 2024). "Other studies have implicated GPD2 in different bioenergetic roles such as OXPHOS regulation in thyroid cancer 25, glycolysis regulation in glioma and liver cancer 26, 73, and G3P-driven ATP synthesis activation." (PMID 36632231, 2023). "In further support of the bioenergetic role of GPD2, the overexpression of GPD2 in thyroid cancer cells increased mitochondrial respiration and ATP production, resulting in increased cell growth." (PMID 38689091, 2024). "In line with the finding that GPD2 is a target of metformin in gluconeogenesis, metformin was shown to lower GPD2 expression for its suppressive activity on thyroid cancer." (PMID 38689091, 2024). "Among the available studies, studies on the effect of metformin on thyroid cancer have focused on the bioenergetic contribution of GPD2 to cancer growth." (PMID 38689091, 2024). "More importantly, thyroid cancers with higher GPD2 levels and metastatic tumors derived from them responded better to metformin than did those with lower GPD2 levels." (PMID 38689091, 2024). "Second, metformin was shown to lower the expression of GPD2 and thus OXPHOS activity in thyroid cancer, which was responsible for its antithyroid cancer effect." (PMID 38689091, 2024). "The inhibition of GPD2 is related to a reduction in oxidative phosphorylation, which has a negative role on thyroid cancer cell growth." (PMID 39054490, 2024).
glioma (8 papers, 2022 to 2024). A benign or malignant brain and spinal cord tumor that arises from glial cells (astrocytes, oligodendrocytes, ependymal cells). "In glioma, macrophage-derived IL-1β induces the activation of GPD2 through interaction with PKCδ, ultimately leading to enhanced glycolysis and proliferation." (PMID 38689091, 2024). "Blockade of IL-1β generation or inhibition of PKCδ, GPD2 pT10 provides us with potential treatment strategies for glioma." (PMID 37012233, 2023). "IL-1β released by GAMs can also promote the phosphorylation and glycolysis of glycerol-3-phosphate dehydrogenase 2 (GPD2) in glioma cells, thereby accelerating tumor proliferation and growth." (PMID 36466873, 2022). "Blocking IL-1β generated by macrophages or Inhibition of PKCδ or GPD2 pT10 in glioma cells attenuated the glycolytic rate and proliferation of glioma cells." (PMID 35600367, 2022). "Furthermore, IL-1β, produced by M2 macrophages, activates the phosphorylation of glycerol-3-phosphate dehydrogenase (GPD2) on threonine 10 (GPD2 pT10) in glioma cells, which enhances the affinity of GPD2 pT10 to substrate, and improves the catalytic rate of glycolysis in glioma cells." (PMID 38632627, 2024). "In addition, M2 macrophages produce IL-1β, which plays a vital role in the phosphorylation of the glycolytic enzyme glycerol-3-phosphate dehydrogenase (GPD2) at threonine 10 (GPD2 pT10) through phosphatidylinositol-3-kinase-mediated activation of protein kinase-delta (PKCδ) in glioma cells." (PMID 37012233, 2023). "In contrast, activation of GPD2, which alters its substrate affinity, preferentially converts G3P to DHAP and transforms it into glycolytic catalysis, thus promoting the proliferation of glioma cells." (PMID 39509399, 2024).
prostate carcinoma (7 papers, 2014 to 2024). A carcinoma that arises from epithelial cells of the prostate gland. "In prostate cancer cells, study found that GPD2-associated mRNA was higher than in normal prostate epithelial cells and that upregulation of GPD2 promoted an overall increase in ROS production and likely contributed to cancer progression due to enhanced intracellular glycolysis capacity." (PMID 39054490, 2024). "Notably, although mitochondrial glycerophosphate dehydrogenase (GPD2) has been implicated in the reoxidation of cytosolic NADH via the ETC in prostate cancer, due to compromised mitochondrial functions, this mechanism is unlikely to be at play in SCO2‐deficient HCT116 cells." (PMID 35302710, 2022). "Along with the increased activity of GPD2 in prostate cancer cells, prostate cancer cells produce 2- to 3-fold more H2O2147 and express higher levels of antioxidant enzymes, including catalase, MnSOD, and CuZnSOD, than normal prostate epithelial cells." (PMID 38689091, 2024). "The involvement of GPD2-mediated oxidative metabolism, e.g., oxygen consumption and ROS production, has also been described in prostate cancer cells compared to normal epithelial prostate cells." (PMID 38689091, 2024). "The role of GPD2 in producing ROS is a poorly investigated metabolic side-reaction with profound implications for the proliferation of prostate cancer cells." (PMID 24521925, 2014). "GPD2 emerged as a substantial source of H2O2 in the pro-oxidative environment of the prostate cancer cell lines PC-3, LNCaP, DU145, and CL1." (PMID 24521925, 2014). "In prostate cancer, the promote GPD2 expression may result in the progression of the cancer through a highly glycolytic environment induce the overall increase in ROS generation." (PMID 39054490, 2024). "A study on prostate cancer cells proposed GPD2 as an ROS producer in cancer progression." (PMID 36632231, 2023). "In particular, PC-3 cells, which are derived from aggressive metastatic adenocarcinoma, displayed the highest GPD2 activity among the examined prostate cancer cell lines, generating up to 4-fold higher amounts of H2O2 compared to normal prostate epithelial cells." (PMID 24521925, 2014). "Furthermore, GPD2 inhibition led to anti-cancer effects in a prostate cancer cell line." (PMID 36677837, 2023).
diabetes (6 papers, 2008 to 2019). "In the diabetic sternohyoid, three of the five calcium channel genes with decreased expression (Fstl1, Atp2b3, Eef2k, Gpd2, Myl6b) were decreased in previous diabetes studies." (PMID 24199937, 2013). "A thorough functional understanding of GPD2 may lead to drug development in other disease models, like diabetes and atherosclerosis." (PMID 24521925, 2014). "In later years, researchers found GPD2 is the target gene for many diseases, such as febrile seizures, nonspecific mental retardation, and diabetes." (PMID 31815134, 2019). "From fourteen genes in the OMIM description of T2DM (Diabetes mellitus, noninsulin dependent, #125853,) five genes have a significant score in our study: Retn, Gpd2, Vegfa, Irs2 and Tcf2." (PMID 18590522, 2008).
gastric cancer (3 papers, 2024 to 2025). A primary or metastatic malignant neoplasm involving the stomach. "Yang, through cell experiments, it was found that TS inhibited the proliferation of gastric cancer cells and promoted the apoptosis of gastric cancer cells by inhibiting glycolysis mediated by GPD2." (PMID 39338278, 2024). "Associations of ABCC8/KCNJ11, DPP4, GLP1R, GPD2, PPARG, PRKAB1, and SLC5A2 with anal carcinoma, cardia cancer, gastric cancer, HCC, ICC, pancreatic cancer, and rectum cancer were revealed in two-sample MR analyses." (PMID 38504335, 2024).
liver cancer (3 papers, 2023 to 2024). An epithelial or non-epithelial malignant neoplasm that arises from the liver. "Moreover, GPD2 expression and activity were higher in prostate and liver cancer cell lines and tissues than in their normal counterparts." (PMID 38689091, 2024). "Esculetin (at a concentration of 50 mM) was effective against HepG2 liver cancer cells, by binding to three potential targets (phosphoglycerate kinase 2 (PGK2), glycerol-3-phosphate dehydrogenase (GPD2) and glucose-6-phosphate isomerase (GPI))." (PMID 37175299, 2023).
type 2 diabetes (3 papers, 2009 to 2021). "The peak on chromosome 2 encompasses one interesting gene, GPD2, which encodes protein to localize to the inner mitochondrial membrane, and also contributes to the genetic liability of type 2 diabetes." (PMID 22384028, 2012).
atherosclerosis (2 papers, 2014 to 2020). A disease characterized by the build-up of fatty material and calcium deposition in the arterial wall resulting in partial or complete occlusion of the arterial lumen. "Three proteins, including PON1, APOA1, and GPD2, involved in atherosclerosis, cardiovascular disease, and lipid metabolism, were selected for validation via western blotting." (PMID 32566106, 2020).
glioblastoma (2 papers, 2024 to 2025). The most malignant astrocytic tumor (WHO grade IV). "GAM-released IL-1β can also be used to stimulate the formation of vasculogenic brain oedema in glioblastoma cells by promoting glycerol-3-phosphate dehydrogenase 2 (GPD2) phosphorylation and glycolysis, thereby accelerating tumor proliferation and growth." (PMID 40061015, 2025).
insulin-dependent diabetes (2 papers, 2014 to 2024). "Compared to these genetic studies performed in rodent systems, GPD2 mutations in human patients were linked to type 2 diabetes, and autoantibodies against GPD2 were detected in insulin-dependent diabetic patients." (PMID 38689091, 2024). "Impaired GPD2 activity was reported in type II diabetic patients and mutations of the GPD2 gene were documented in families of patients with non-insulin-dependent diabetes." (PMID 24521925, 2014).
pancreatic cancer (2 papers, 2023 to 2024). "Furthermore, ABCC8/KCNJ11, DPP4, GLP1R, PRKAB1, and GPD2 shared causal variants within anal cancer, HCC, ICC, pancreatic cancer, and rectum cancer according to the colocalization analyses." (PMID 38504335, 2024).
anal carcinoma (1 paper, 2024). "Weak evidence indicated the connections of GLP1R, GPD2, and PRKAB1 with anal carcinoma, cardia cancer, ICC, and rectum cancer." (PMID 38504335, 2024).
asthma (1 paper, 2025). "Of the remaining 4 loci, three appeared to affect only asthma: 2q24.1 near GPD2, 8p23.1a near SGK223, and 8p23.1d near DEFB136." (PMID 41213931, 2025).
autism (1 paper, 2024). Persistent deficits in social interaction and communication and interaction as well as a markedly restricted repertoire of activity and interest as well as repetitive patterns of behavior. "In this respect, GPD2 has been deleted and mutated in autism, and IMMP2L is strongly linked with autism inheritance; however, the molecular basis of these associations has yet to be established." (PMID 38256063, 2024). "Given these GPD2 associations with autism/behavioural change, it is possible that the lower comparative incidence of autism in females with hemizygous deletions of GPD2 may be due to a much higher expression level of GPD2 in females." (PMID 38256063, 2024).
B cell lymphoma (1 paper, 2016). "Notably, re-evaluation of expression profiling data following acute TTP expression in Myc-driven B cell lymphoma found that mRNAs encoding the metabolic enzymes Dlat, Idh3a, Gpd2, and Cycs are also rapidly down-regulated targets of TTP in this context (data not shown)." (PMID 27825143, 2016).
Candida infection (1 paper, 2020). "Gpd2 on Candida was shown to bind to human epithelial and endothelial cells, which might support Candida infection and dissemination in the host." (PMID 32765510, 2020).
cardiomyopathy (1 paper, 2023). A disease of the heart muscle or myocardium proper. "Twelve of the 52 mouse models identified with cardiomyopathy (Acadv1, Fxn, Mto1, Taco1, Hmgcs2, Mpv17, Opa1, Pnpla8, Tmem126b, Gpd2, Mpv17, Micu1) showed that the presence of cardiomyopathy can be dependent on the degree of stress." (PMID 37103033, 2023).
cervical cancer (1 paper, 2025). A primary or metastatic malignant neoplasm involving the cervix. "In cervical cancer, lactate secreted by tumor cells increases H3K18la levels and promotes M2 polarization by upregulating glycerol-3-phosphate dehydrogenase 2 (GPD2), thereby supporting tumor progression." (PMID 40584966, 2025).
Cirrhosis (1 paper, 2023). A chronic disorder of the liver in which liver tissue becomes scarred and is partially replaced by regenerative nodules and fibrotic tissue resulting in loss of liver function. "A total of 97 HCC patients with cirrhosis were selected from TCGA, and 5 genes (ADH1C, ACSL4, GPD2, ME1, NCAPH2) were selected to construct a FAM-related prognosis signature via Lasso–Cox regression using this cohort." (PMID 36671526, 2023).
delirium (1 paper, 2025). A disorder characterized by confusion; inattentiveness; disorientation; illusions; hallucinations; agitation; and in some instances autonomic nervous system overactivity. "There were eight protective genes (DHODH,DHRS7B,TOP1MT,CASP8,GFM1,CPT1B,TK2,GPD2), and four genes (SCP2,DMPK,GSTK1,SIRT3) that increased delirium risk, as shown inFigure 2, withp = 0.05 (dotted line); and false discovery rate (FDR) < 0.05 (red asterisks)." (PMID 41330563, 2025).
developmental disability (1 paper, 2019). Disorders in which there is a delay in development based on that expected for a given age level or stage of development. "The family members share an inherited variant of uncertain significance (VUS) in GPD2, a gene that was previously associated with developmental disability but here is insufficient by itself to cause ASD." (PMID 31893020, 2019).
glucose metabolism disorders (1 paper, 2025). "Among the remaining 11 genes associated with CVS, GPD1L and GPD2, both involved in glucose metabolism, stand out, suggesting a potential link between glucose metabolism disorders and CVS." (PMID 39981435, 2025).
Hyperglycemia (1 paper, 2019). An increased concentration of glucose in the blood. "In mice, loss of Gpd2 is associated with decreased insulin secretion; loss of Neurod1 is associated with hyperglycemia; loss of Mapk8ip1 is associated with abnormal gluconeogenesis and increased insulin sensitivity." (PMID 31776723, 2019).
Intellectual disability (1 paper, 2020). "Similarly, the Gpd2 gene is found to be associated with intellectual disability in humans and positively affected due to circadian desynchrony in mice." (PMID 33114225, 2020).
lipid metabolism disorders (1 paper, 2025). "In this study, seven core genes (Amacr, Cyp39a1, Echs1, Gpd2, Osbpl9, Acsl4, and Mcee) closely associated with lipid metabolism disorders in AP were systematically identified through the integration of bioinformatics and machine learning approaches." (PMID 41007695, 2025).
male infertility (1 paper, 2016). The inability of the male to effect fertilization of an ovum after a specified period of unprotected intercourse. "Thus, we suggest that arsenic-induced repression of VDAC3, PRKACA and GPD2 as well as the aberrant increase of L-tyrosine may disrupt the extent of protein tyrosine phosphorylation required for sperm capacitation, which then result in fertilization failure and male infertility." (PMID 27585557, 2016).
Neurodevelopmental delay (1 paper, 2025). "Moreover, functional impairment of GPD2 has been associated with neurodevelopmental delay." (PMID 40995562, 2025).
osteoporosis (1 paper, 2017). A condition of reduced bone mass, with decreased cortical thickness and a decrease in the number and size of the trabeculae of cancellous bone (but normal chemical composition), resulting in increased fracture incidence. "Previous studies from our group have supported the contribution of GPD2, TPM4 and GSN to osteoporosis risk." (PMID 27878450, 2017).
rectum cancer (1 paper, 2024). "GPD2 was associated with rectum cancer (OR = 0.031; 95% CI: 0.002–0.428; P-value = 0.010)." (PMID 38504335, 2024). "Strong evidence uncovering the colocalization between the GPD2 and rectum cancer." (PMID 38504335, 2024). "Therefore, in our study, we conducted a detailed investigation into the three drug targets of metformin (ETFDH, GPD2, and PRKAB1), and the discovery cohorts and integrated results revealed that GPD2 has an inhibitory effect on the occurrence of rectum cancer." (PMID 38504335, 2024).
thyrotoxicosis (1 paper, 2022). A hypermetabolic syndrome caused by the elevation of thyroid hormone levels in the serum. "The expression of T3-regulated genes, including Hr, Dio1, Gpd2, Dbp, and Klf9, was markedly elevated in Dio3–/– fetuses compared with Dio3+/+ littermates, indicating thyrotoxicosis in all tissues." (PMID 36166296, 2022).